RADX (RPA1 related single stranded DNA binding protein, X-linked)
Description:
Single-stranded DNA-binding protein recruited to replication forks to maintain genome stability. Prevents fork collapse by antagonizing the accumulation of RAD51 at forks to ensure the proper balance of fork remodeling and protection without interfering with the capacity of cells to complete homologous recombination of double-strand breaks.
Synonyms: CXorf57; FLJ14191; FLJ10178
Tractability: PROTAC: ubiquitination databases record sites on it.
Gene: Protein-coding gene on chromosome X (106,611,930 to 106,679,439, forward strand). Ensembl gene ENSG00000147231.
Subcellular location: Chromosome
Subcellular location (Human Protein Atlas): Nuclear speckles
Gene Ontology:
Molecular function: protein binding; RNA binding; single-stranded DNA binding
Biological process: negative regulation of double-strand break repair via homologous recombination; regulation of DNA repair
Cellular component: chromosome; nuclear speck; replication fork
Homologues: Orthologues: chimpanzee RADX (100% identical), macaque RADX (99% identical), dog RADX (88% identical), pig RADX (84% identical), rabbit RADX (80% identical), rat Radx (80% identical), mouse Radx (78% identical), tropical clawed frog radx (40% identical), zebrafish radx (23% identical).
Diseases named in the same sentence as RADX in open-access papers:
RADX is named in the same sentence as 4 diseases in open-access papers, as found by Europe PMC text mining. Sharing a sentence is not in itself a finding about the gene and the disease. The quoted sentences say what the papers report.
lung carcinoma (1 paper, 2022). "Interestingly, this group found that breast and lung cancer patients with higher RADX expression tend to show better survival than those with low RADX expression, highlighting the clinical relevance of these findings." (PMID 36568963, 2022).
cancer (1 paper, 2024). A tumor composed of atypical neoplastic, often pleomorphic cells that invade other tissues. "Although little research has been conducted on RADX in cancer, evidence suggests that inactivation of RADX may confer resistance to chemotherapy and PARP inhibitors in cancer cells." (PMID 38725627, 2024).
RADX also shares sentences with these, for which no sentence is quoted: Asperger Syndrome (1 paper); Seizure (1).